THPO (thrombopoietin)
Diseases named in the same sentence as THPO in open-access papers (continued):
Sharing a sentence is not in itself a finding about the gene and the disease.
Thrombocytosis (continued). "With regard to THPO, several mutations have been described to reduce the physiological inhibition of THPO-mRNA translation leading to higher serum levels of the hormone and consequently thrombocytosis." (PMID 33712866, 2021). "The different thrombopoietin, CgA, and CgB levels in the CgA+ group suggested a difference in the mechanism of thrombocytosis and chromogranin production, compared to that of CgA− CRC patients." (PMID 33383764, 2020). "Humans with the benign germline SNP, K39N (MPL Baltimore), however, actually recapitulate mouse hematopoiesis with thrombocytosis, an elevated plasma THPO level and impaired MPL cell-surface expression." (PMID 32479500, 2020). "Certain inflammatory cytokines, mainly interleukin-6, that increase with inflammation have been noted to stimulate thrombopoietin production and induce thrombocytosis." (PMID 32817656, 2020). "Although the mechanism of thrombocytosis is not completely understood, accelerated megakaryopoiesis due to elevated megakaryocytic growth factors such as thrombopoietin, interleukin (IL)-6, or IL-11 has been assumed." (PMID 32181630, 2020). "In a previous study, the inhibition of thrombopoietin or IL-6 prevented the development of thrombocytosis in mice and significantly enhanced the therapeutic efficacy of paclitaxel in mouse models of epithelial ovarian cancer." (PMID 28903428, 2017). "High MPV and platelet counts supported reactive (inflammatory) thrombocytosis, in which IL-6-mediated thrombopoietin production stimulates platelet production." (PMID 25402479, 2014). "Taken together, visceral adipose tissue may be an additional source of thrombopoietin and IL-6, which may explain thrombocytosis in patients with high vFMR; however, further studies are needed to prove this." (PMID 36681847, 2023). "Combining the effect of thrombocytosis of thrombopoietin and interleukin-6 released by tumour cells, raised platelet counts (opposed to low or normal lymphocyte count) leads to increased PLR and hence worsened oncological outcome in patients as a negative predictor." (PMID 37046847, 2023). "We also considered a tumor-bearing model treated with recombinant thrombopoietin that might simulate paraneoplastic thrombocytosis upon abnormal secretion in various malignancies." (PMID 37872588, 2023). "This is supported by the evidence that silencing IL-6 and thrombopoietin abrogates thrombocytosis in animal models, and pre-treatment thrombocytosis in patients with EOC tends to be related to advanced stage, higher grade, higher level of CA-125, larger ascites volume, and larger tumor residual." (PMID 36158646, 2022). "The neutrophilia and thrombocytosis seen in our data could be the result of cytokine stimulation of granulocyte-colony stimulating factor and thrombopoietin." (PMID 35180232, 2022). "If the first genetic screening remains without positive findings, testing for THPO mutations in the 5′UTR region in order to exclude further causes of hereditary thrombocytosis is recommended." (PMID 33712866, 2021). "In certain cases, GOF mutations in THPO lead to increased TPO synthesis and thrombocytosis." (PMID 28955303, 2017). "Moreover, the inhibition of thrombopoietin and IL-6 expression abrogated thrombocytosis in tumor-bearing mice and significantly enhanced the therapeutic efficacy of paclitaxel in mouse models of epithelial ovarian cancer." (PMID 28903428, 2017). "The thrombopoietin produced by tumor may have a direct effect on thrombocytosis/thrombosis occurrence in patients with ovarian cancer." (PMID 28465688, 2017). "Although some patients harbor germline mutations within the THPO (thrombopoietin) or MPL (thrombopoietin receptor) genes, the molecular defect still remains unknown in most instances of hereditary thrombocytosis." (PMID 25525531, 2014). "Indeed, silencing of the IL-6 and thrombopoietin genes markedly abrogated thrombocytosis (and halted tumor progression) in a mouse model of epithelial ovarian cancer." (PMID 25469228, 2014).
Thrombocytosis (continued). "In murine models of JAK2 deletion in platelets and megakaryocytes (Mk), thrombocytosis via reduced thrombopoietin turnover and expansion of Mk-biased haematopoietic stem cell lineages has been observed and may offer an additional explanation for platelet recovery in this patient." (PMID 40124999, 2025). "Moreover, a rise in thrombopoietin values and IL-6 was observed, which explains the existence of a paracrine circuit where the increase in thrombopoietic cytokines leads to paraneoplastic thrombocytosis, which stimulates tumor growth." (PMID 36837431, 2023). "Finally, tumours may also release thrombopoietin and interleukin-6—which stimulate thrombocytosis through various signalling pathways." (PMID 37046847, 2023). "This thrombocytosis (defined as circulating thrombocytes of more than 450.000/mm3) is determined by aberrant paracrine signaling via a high circulating level of interleukin 6 (a by-product of the tumor microenvironment) and thrombopoietin (produced by the liver)." (PMID 35626439, 2022). "IL-6 is likely to be the main driver, acting synergistically with other interleukins to increase thrombopoietin, of which visceral adipose tissue itself may be an additional source of thrombopoietin, which in turn stimulates megakaryocyte production, leading to thrombocytosis." (PMID 39544233, 2024). "Paracrine secretion of IL-6 from tumor cells stimulates the production of thrombopoietin (TPO), resulting in megakaryopoiesis and platelet genesis and leading to a status of thrombocytosis and hypercoagulability known as Trousseau’s syndrome." (PMID 37880772, 2023). "In one study, orthotopic ovarian-mouse models revealed tumor-derived, interleukin-6-stimulated, hepatic-thrombopoietin (TPO) synthesis and paraneoplastic induction of thrombocytosis." (PMID 34367949, 2021). "The proposed mechanism involves elevated blood glucose activating neutrophils, leading to the release of S100A8/A9 proteins, which stimulate thrombopoietin (TPO, THPO) production upon interacting with the RAGE receptor on Kupffer cells, resulting in increased thrombocytosis." (PMID 39375979, 2025). "One mechanism that could explain thrombocytosis in many tumors could be tumor-derived interleukin-6 (IL-6), which stimulates thrombopoietin (TPO) production in the liver, thereby promoting megakaryopoiesis and thrombocytosis." (PMID 36901997, 2023). "Thrombocytosis is a paraneoplastic syndrome of ovarian cancer, and the mechanism is mainly explained by the higher plasma levels of thrombopoietin and IL-6 in patients with thrombocytosis compared to those without thrombocytosis." (PMID 36681847, 2023). "Injection of thrombopoietin into Balb/C nude mice prior to infusion of PC3 prostate cancer cells decreased the extent of skeletal lesions and metastatic tumor burden despite concomitant thrombocytosis due to expansion of resident MKs." (PMID 32400122, 2020). "Though thrombopoietin levels were not done, the thrombocytosis may be a paraneoplastic manifestation of HCC." (PMID 27990204, 2009). "However, In agreement with our observations, thrombocytosis was abrogated and in vitro HPC proliferation, megakaryocyte number and size, and spleen size were reduced in their JAK2V617F/THPOdel/del mice, indicating THPO dependence in their JAK2V617F transgenic mouse model." (PMID 32479500, 2020). "Therefore, a prospective, real-life observational cohort study was conducted where paraneoplastic thrombocytosis was investigated within diabetic and nondiabetic CRC cohorts through the changes in platelet counts, plasma interleukin-6, and thrombopoietin levels." (PMID 35071777, 2022).
portal hypertension (51 papers, 2009 to 2025). Increased blood pressure in the portal venous system. "The liver disease had an association with coagulopathy because all coagulation factors and thrombopoietin are produced in the liver cells." (PMID 34074308, 2021). "They include sequestration of platelets in spleen due to portal hypertension, decreased thrombopoietin levels, bone marrow suppression because of underlying liver disease present and auto-antibody destruction of platelets." (PMID 33369474, 2020). "Our data suggest that cancer patients with underlying liver disease may have greater sensitivity to myeloablative conditioning and supplementing THPO mimetics may help alleviate the adverse effects associated with myeloablative conditioning in these patients." (PMID 34463253, 2021). "First, severe chronic liver disease typically induces hypersplenism through portal hypertension and reduced hepatic thrombopoietin production, leading to increased platelet clearance and diminished platelet production." (PMID 40321812, 2025). "As liver function deteriorates, the resultant portal hypertension and reduced thrombopoietin levels contribute to a decline in platelet count." (PMID 40271064, 2025). "The decreased platelet count suggests advanced portal hypertension, splenic sequestration, and reduced liver thrombopoietin synthesis." (PMID 40281590, 2025). "Platelets tend to decrease in liver disorders, with mechanisms including decreased thrombopoietin production as well as sequestration of platelets in enlarged spleen in those with cirrhosis and portal hypertension." (PMID 40723273, 2025). "This is particularly true in patients with LC, where factors such as portal hypertension-induced hypersplenism and reduced hepatic synthesis of thrombopoietin and coagulation factors can lead to low platelet counts and impaired coagulation." (PMID 39594268, 2024). "In fact, patients with liver cirrhosis often present with a low platelet count that reflects the splenomegaly due to portal hypertension and the altered hepatic synthesis of thrombopoietin." (PMID 37240934, 2023). "Possible mechanisms include liver cirrhosis with splenomegaly and decreased thrombopoietin production in patients with advanced liver disease." (PMID 35453642, 2022). "Coagulopathy due to liver disease is a result of all coagulation factors involved in the generation of a fibrin clot, and thrombopoietin is produced by liver cells." (PMID 34074308, 2021). "A greater reduction in thrombopoietin production occurs when liver disease is exacerbated, like in a higher stage of fibrosis." (PMID 34659664, 2021). "Some mechanisms for thrombocytopenia induced by liver disease have been explained, such as a decrease in Thrombopoietin as an endogenous hormone released by liver, which plays a main role in this complication." (PMID 34659664, 2021). "Other factors that potentially contribute to cytopenias in liver disease have been proposed, including insufficient thrombopoietin (TPO) production by the liver, and marrow injury due to hepatitis viruses, alcohol abuse and poor diet." (PMID 26865982, 2016). "Thrombopoietin (TPO) has been implicated in the process of liver regeneration and was found to correlate with hepatic function in patients with liver disease." (PMID 25611592, 2015). "PLT, the variable with the greatest AUC among the components of APPCI, correlates with the degree of portal hypertension and, to a lesser extent, with hepatic function and reduced thrombopoietin synthesis." (PMID 24282481, 2013). "Liver disease may contribute to relapse through multiple mechanisms, including residual hypersplenism, altered thrombopoietin production, and liver-induced coagulopathy." (PMID 40282869, 2025). "In patients with cirrhotic liver disease, the platelet count is frequently observed to be reduced, a phenomenon attributed to two primary factors: the sequestration of platelets in the spleen and the diminished production of thrombopoietin." (PMID 37746529, 2023).
portal hypertension (continued). "In addition, the thrombopoietin, predominantly produced by the liver, is markedly reduced in advanced-staged liver disease, which also contributes to reduced thrombopoiesis in the bone marrow." (PMID 36148462, 2022). "Herein, it was hypothesized that alleviation of the severity of liver disease by the anti-fibrotic and antioxidant properties of melatonin may lead to the increased production of thrombopoietin by the liver." (PMID 34659664, 2021). "Decreased thrombopoietin production in dACLD patients may have ameliorated the impact of portal hypertension on platelet counts." (PMID 33000389, 2020). "Decreased thrombopoietin (TPO) levels, hypersplenism secondary to portal hypertension, and myelosuppression induced by antiviral therapy may all lead to decreased PLT." (PMID 37641600, 2023). "A low platelet count is associated with advanced liver fibrosis through the altered production of thrombopoietin and is independent of demographic and biochemical characteristics, hepatic necroinflammatory activity, portal hypertension, and splenomegaly." (PMID 24616815, 2014). "Low platelet count was associated with advanced liver fibrosis through the altered production of thrombopoietin, and this occurred independent of demographic and biochemical characteristics, hepatic necroinflammatory activity, portal hypertension and splenomegaly." (PMID 28052021, 2017).
hypersplenism (32 papers, 2012 to 2026). Overactive functioning of the spleen, resulting in excessive destruction of blood cells. "The decreased PLT may be caused by hypersplenism and the decreased thrombopoietin production associated with damaged liver cells in liver fibrosis and cirrhosis patients." (PMID 32846758, 2020). "Their pathogenesis is multifactorial, comprising hypersplenism-related sequestration, decreased synthesis of hematopoietic growth factors, such as thrombopoietin, bone marrow suppression, immune-mediated destruction, and systemic inflammation." (PMID 42253373, 2026). "On one hand, disruption of hepatic sinusoid architecture—such as capillarization mediated by LN-induces hypersplenism and reduced thrombopoietin (TPO) synthesis, resulting in the reduction of PLT." (PMID 40809427, 2025). "Low platelet counts, on the other hand, are already well-known to be associated with liver fibrosis and cirrhosis owing to the impairment of thrombopoietin production and hypersplenism in such conditions." (PMID 38337781, 2024). "In cases of co-infections with hepatitis viruses, liver damage leads to decreased production of thrombopoietin and, due to hypersplenism, increased destruction of platelets." (PMID 39330902, 2024). "The etiology of a low PLT count in NAFLD remains unclear, with the proposed factors including hypersplenism, bone marrow hypoplasia, decreased peripheral blood cell survival, and thrombopoietin insufficiency." (PMID 39200880, 2024). "There may be a role for long-term use of thrombopoietin mimetic agents and histone deacetylase inhibitors for managing recalcitrant cytopenias and hypersplenism." (PMID 26258116, 2015). "In liver cirrhosis, albumin levels and the count of platelets may be diminished due to the liver’s impaired ability to synthesize albumin, together with the presence of hypersplenism, decreased thrombopoietin synthesis, and bone marrow suppression regarding platelets." (PMID 41301494, 2025).
Cirrhosis (31 papers, 2009 to 2025). A chronic disorder of the liver in which liver tissue becomes scarred and is partially replaced by regenerative nodules and fibrotic tissue resulting in loss of liver function. "A reduced hepatic thrombopoietin production has also been claimed as a factor causing platelet decrease in patients with cirrhosis." (PMID 23967022, 2013). "A possible explanation may be that the decreased PLT counts are due to splenomegaly and the decreased thrombopoietin production associated with liver cell failure in cirrhosis patients." (PMID 28938634, 2017). "Previous studies have reported reduced thrombopoietin levels in patients with cirrhosis, which affects thrombopoiesis." (PMID 39529828, 2024). "Liver is an important site of thrombopoietin production and its levels are decreased in patients with cirrhosis." (PMID 27800187, 2016). "However, the effective contribution of the THPO/THPOR axis in the progression from cirrhosis to HCC remains to be clarified." (PMID 33673041, 2021). "Furthermore, other factors, including toxic effects on the bone marrow induced by drugs or cirrhosis, and reduced thrombopoietin synthesis, could also lead to a decreased platelet count." (PMID 35911970, 2022). "The mRNA and protein expression levels of THPO, VEGF-A, and their receptors were examined, compared, and correlated in paired cancerous and LC tissues from 26 cirrhosis-related HCC patients, using qRT-PCR and immunohistochemistry." (PMID 33673041, 2021).
liver fibrosis (22 papers, 2011 to 2025). "Hepatitis C virus infection is highly associated with thrombopoietin levels, platelet counts, liver function impairment, and the severity of hepatic fibrosis." (PMID 25013658, 2013). "Previous studies also have found that decreased platelet counts were associated with progression of liver fibrosis, which is due largely to decreased production of thrombopoietin by hepatocytes." (PMID 24260428, 2013). "A low platelet count has also been associated with advanced liver fibrosis through the altered production of thrombopoietin." (PMID 21853071, 2011). "In addition, progression of liver fibrosis was linked with decreased production of thrombopoietin by hepatocytes, and hence reduced platelet production." (PMID 30305679, 2018). "With the advancement of liver fibrosis, there is a reduction in thrombopoietin-producing capability by the liver, reducing platelet production." (PMID 40954485, 2025). "Progression of liver fibrosis reduces the production of thrombopoietin by hepatocytes and, hence, reduced platelet production." (PMID 33013622, 2020). "Common factors affecting platelet count in patients with chronic liver disease include hepatic fibrosis, necroinflammation, and thrombopoietin." (PMID 32793612, 2020). "Common factors affecting platelet count in patients with CHC are liver fibrosis, hepatic necroinflammation, and thrombopoietin." (PMID 31029101, 2019). "In addition, progression of liver fibrosis reduces the production of thrombopoietin and, hence, reduces platelet production." (PMID 34879856, 2021). "THPO has not been shown to be related to lung injury, but plays a protective role in liver fibrosis." (PMID 26289430, 2015).